ATG7 (autophagy related 7)
Diseases named in the same sentence as ATG7 in open-access papers (continued):
Sharing a sentence is not in itself a finding about the gene and the disease.
hepatocellular carcinoma (46 papers, 2012 to 2025). A malignant tumor that arises from hepatocytes. "Studies have reported that ATG7 deficiency in mice leads to hepatocellular carcinoma by activating the Yap metabolic pathway." (PMID 40276062, 2025). "Mice with hepatocyte-specific deletion of autophagy-related 7 (Atg7ΔHep mice) develop hepatoma, suggesting that autophagy deficiency could be a factor in the initiation of tumorigenesis." (PMID 35321438, 2022). "Although autophagy defects result in tumor formation, mosaic deletion of Atg5 in mice or Atg7 in mouse livers produces only benign hepatomas, suggesting that complete and specific autophagy deficiency promotes liver tumor initiation but restricts progression to malignant disease." (PMID 34829743, 2021). "The study in mice had shown that liver-specific knockout of ATG7 develops into hepatocellular adenocarcinoma." (PMID 36829596, 2023). "Other studies have pointed out that DANCR induces the proliferation, colony formation, and autophagy of hepatoma cells by increasing ATG7 and inhibiting miR-222-3p." (PMID 37125193, 2023). "We investigate the role of lncRNA TINCR in miR-375/ATG7-mediated regulation of hepatocellular carcinoma proliferation and invasion." (PMID 36157234, 2022). "For instance, TGF-β activates autophagy in human hepatocellular carcinoma cells by upregulating the levels of Beclin 1, Atg5 and Atg7." (PMID 36230955, 2022). "A study on mice with tissue-specific knockout of Atg7 in hepatocytes revealed that they develop hepatocellular carcinoma, similar to what we have found to be correlated with the D522E variant." (PMID 40396019, 2022). "We have previously reported that CD13 induces autophagy through the P38/Hsp27/CREB/ATG7 pathway to promote chemoresistance in hepatocellular carcinoma cells." (PMID 34045966, 2021). "Our results are in agreement with previous studies showing that TGF-β induces the expression of the autophagy-related genes BECN1, ATG5, and ATG7 through the SMAD signaling pathway in hepatocellular cancer cells, leading to the activation of autophagy." (PMID 34681055, 2021). "Treatment of hepatoma cells with the antineoplastic tyrosine kinase inhibitor drug sorafenib inactivated mTORC1 resulting in increased accumulation of autophagosomes, LC3B II, and autophagic flux, whereas ATG7 knockdown sensitized hepatoma cells to sorafenib." (PMID 33976943, 2021). "Apigenin has been proven to sensitize hepatocellular carcinoma through downregulating the levels of autophagy-related 7 (ATG7) and nuclear factor erythroid 2-related factor 2 (NFE2L2, also known as NRF2)." (PMID 33066509, 2020). "Meanwhile, HOTAIR has also been shown to enhance cell autophagy through up-regulation of ATG3 and ATG7 in hepatocellular carcinoma." (PMID 32396526, 2020). "Previous studies demonstrated ATG7 and mTOR as the target genes of miR-199a-5p involved in the regulation of the autophagic process in hepatocellular carcinoma and hypertrophic hearts." (PMID 31636666, 2019). "The concomitant inhibition of autophagy by CQ or genetic knockdown Atg7 sensitized hepatoma cells to sorafenib." (PMID 24765136, 2014). "A high expression of Atg7 can lead to the malignant enhancement of hepatocellular carcinoma." (PMID 37461263, 2023). "For example, p62 levels are increased in hepatomas developed from Atg7 knockout mice." (PMID 35725745, 2022). "It was reported that knockout of ATG7 could lead to a significant reduction in tumorigenesis in a mouse model of hepatocellular carcinoma." (PMID 36203871, 2022). "Since FGF21 or other endocrine FGF such as FGF19 can affect tumor growth, we hypothesized that FGF21 produced by Atg7-knockout (KO) hepatocytes may affect the behavior of Atg7-KO hepatoma in an autocrine manner." (PMID 35321438, 2022). "Furthermore, decreased expression of autophagic genes (Atg5, Beclin1, Atg7) and autophagic activity was observed in hepatocellular carcinoma (HCC)." (PMID 34440583, 2021).
hepatocellular carcinoma (continued). "Furthermore, decreased expression of autophagy-related genes such as ATG5, ATG7, and Beclin-1 has been observed in hepatocellular carcinoma (HCC) cells, and our laboratory has confirmed that autophagy deficiency due to ATG5 knockout can induce malignant cellular transformation." (PMID 39519774, 2024). "Retinoid acid receptor is a transcription factor that can bind to the 5’-flanking region of the Atg7 proximal promoter, regulating ATG7 transcription and hepatocellular carcinoma (HCC) progression." (PMID 38553562, 2024). "However, a subsequent study reported that Atg7‐null mice develop hepatocellular carcinoma." (PMID 34725936, 2021). "In addition, some studies found that lncRNAs and Phosphoinositides (PIs) could activates autophagy by upregulating ATG3 and ATG7 in hepatocellular carcinoma." (PMID 29895332, 2018). "In this context, Zhao and colleagues represented that through the P38/Hsp27/CREB/ATG7 pathway, CD13 [romotes chemoresistance in hepatocellular carcinoma cells by inducing autophagy." (PMID 39315094, 2024). "Expression assays in hepatocellular cancer tissues have revealed over-expression of DANCR and ATG7, and down-regulation of miR-222-3p." (PMID 35590326, 2022). "Another study in hepatocellular carcinoma cells has shown over-expression of DANCR and ATG7, and down-regulation of miR-222-3p." (PMID 35590326, 2022). "Furthermore, a reduced expression of autophagy genes (ATG5, ATG7 and Beclin-1) has been observed in hepatocellular carcinoma (HCC) cells." (PMID 33743781, 2021). "ATG7 and NFE2L2 are downregulated by apigenin and directly targeted by miR-520b and miR-101, respectively, in hepatocellular carcinoma." (PMID 33066509, 2020). "In hepatocellular carcinoma (HCC) cells, the conversion of LC3-I into LC3-II is inhibited by miR-375 via targeting of ATG7." (PMID 32517694, 2020). "Moreover, autophagy triggered by starvation initiates EMT and invasion in hepatocellular carcinoma (HCC) cells through TGF-β/Smad3 signaling, and inhibition of autophagy by depleting Atg3 or Atg7 abolishes this effect." (PMID 38741166, 2024). "The requirement for ATG7 and STX17, and co-localization between APOE and autophagosome marker LC3A that we observe in HepG2 are consistent with previous work showing APOE colocalization and co-immunoprecipitation with LC3 in hepatoma cells." (PMID 34982109, 2022). "LncRNA HOTAIR has been demonstrated to be overexpressed in hepatocellular carcinoma (HCC), also promoting autophagy in these cells by upregulating ATG3 and ATG7 at mRNA and protein levels." (PMID 35309939, 2022). "The finding that Atg5-/- or Atg7-/- mouse livers give rise to benign adenomas, but not malignant hepatocellular carcinomas, is likely indicative of the opposing roles that autophagy may plays at different stages of tumorigenesis." (PMID 23181220, 2012).
melanoma (38 papers, 2013 to 2025). A malignant, usually aggressive tumor composed of atypical, neoplastic melanocytes. "Reduced expression of ATG5 and ATG7 has been reported in melanoma, while loss of ATG7 promotes hepatic tumor formation." (PMID 41516242, 2025). "For example, forced Atg7 3′ UTR lengthening in mouse melanoma suppresses ATG7 protein levels, slows tumor growth, and improves host survival; similarly, in clinical human melanoma, a long ATG7 3′ UTR is associated with significantly prolonged patient survival." (PMID 38302465, 2024). "For example, injection of autophagy-proficient mouse melanoma cells into autophagy-deficient mouse hosts with Atg7 deletion resulted in reduced tumorigenic growth of the cancer cells." (PMID 34298710, 2021). "Of note, as for the Atg7-deficient BrafV600E; Pten−/− driven melanomas, complete loss of Atg5 reduced tumor formation." (PMID 31998652, 2019). "ATG7 deficiency inhibits the growth of BrafV600E-driven melanoma with increased oxidative stress and senescence." (PMID 28624205, 2017). "We first assessed mutation status of ATG7 across the 424 patients in TCGA’s melanoma cohort." (PMID 38302465, 2024). "The simplest interpretation of this observation was that the loss of Atg7 and by extension autophagy could prevent melanoma, implying that basal autophagy could contribute to tumorigenic process in certain context." (PMID 36670319, 2023). "Moreover, our study, for the first time, associates the expression of ATG7 with melanoma development and progression." (PMID 34458153, 2021). "It has also been demonstrated that treatment with dabrafenib more markedly inhibited growth and induced senescence in tumors derived from ATG7-deficient melanoma cells, further indicating that efficient autophagic flux limits the response of melanoma cells to anti-cancer drugs." (PMID 32340261, 2020). "White's group has recently demonstrated that, once autophagy is systemically depleted in a mouse model with conditional whole-body Atg7 deficiency or when autophagy-proficient melanoma cells are subcutaneously injected into mice, melanoma growth significantly slows down." (PMID 31998652, 2019). "Moreover, melanoma autophagy suppression due to autophagy-related-7 (Atg7) deficiency in a BRAFV600E-mutant, phosphatase and tensin homolog (Pten)-null mouse model induces oxidative stress and senescence of melanoma cells and ultimately impedes melanoma development." (PMID 36003368, 2022). "The knockout of ATG5 or ATG7 significantly inhibited the survival of melanoma cells under low-nutrient conditions." (PMID 40497999, 2025). "Consistent with the results obtained with the inhibitors, silencing the expression of Atg7 and Atg12, essential components of the autophagy machinery, allowed melanoma cells to partially resist death and reduced LDH release after exposure to TRI-03." (PMID 40486906, 2025). "We observed that patients whose tumors expressed a longer ATG7 3′ UTR exhibited significantly better progression-free survival, consistent with our finding that forcing long Atg7 3′ UTR usage slowed mouse melanoma growth." (PMID 38302465, 2024). "We next explored lung metastasis of cancer cell through intravenous injection of B16 melanoma cells into wild‐type, ATG7‐KO, or SIRT2−/− mice." (PMID 36453571, 2023). "In a genetically engineered melanoma mouse model, Atg7 promotes tumor growth by limiting oxidative stress and senescence." (PMID 36466095, 2022). "Our results emphasize the significance of autophagy for melanoma development and progression, and, for the first time, we provide data on the expression of ATG7 in melanoma." (PMID 34458153, 2021). "Since the expression levels of ATG5 and ATG7 are reduced in melanoma tissues and their expression levels correlated with the outcome of the patients, it is important to decipher the regulatory mechanisms responsible for the observed reduction." (PMID 34458153, 2021).
melanoma (continued). "In another study, it was shown that silencing of ATG7 suppresses the growth of BRAFV600E/PTENNull melanomas, leading to extended survival of tumor-bearing mice." (PMID 34298710, 2021). "We decided to search for novel TFs regulating autophagy, and specifically ATG5 and ATG7, in melanoma." (PMID 34458153, 2021). "As our model develops senescent nevi before invasive melanoma occurs, it is conceivable that acceleration of melanoma onset upon Atg7 deletion is due to a senescence defect." (PMID 33664481, 2021). "Since our previously published and current data show decreased expression of three of the core ATGs (ATG5, ATG7 and Beclin-1) in melanoma, we decided to study the impact of NRF1 and NFE2L2 on the expression of these ATGs." (PMID 34458153, 2021). "Taken together, we identified NRF1 as a novel TF involved in the regulation of ATG5 and ATG7 in melanoma and therefore provide novel insights into the transcriptional regulation of autophagy." (PMID 34458153, 2021). "We demonstrate that the expression of ATG7 is reduced in primary melanoma and in contrast to ATG5, the expression of ATG7 is further reduced in metastatic melanoma tissues." (PMID 34458153, 2021). "In the current study, we observed a significant reduction in ATG5 and ATG7 expression in primary and metastatic melanomas compared to benign nevi." (PMID 34458153, 2021). "The crucial role of autophagy and RONS in melanoma pathophysiology was highlighted using a BRAFV600E mutant, PTEN tumour suppressor gene-null, Atg7-deficient mouse model of melanoma." (PMID 34830947, 2021). "Results from immunohistochemistry show that the expression of ATG5 and ATG7 is significantly reduced in melanoma tissues compared to benign nevi." (PMID 34458153, 2021). "In BrafV600E mice wild-type for Pten (Tyr-Cre:ER Pten+/+ BrafV600E/+), deletion of Atg7 (Tyr-Cre:ER Pten+/+ BrafV600E/+Atg7−/−) significantly accelerated melanoma onset." (PMID 33664481, 2021). "In this model, dabrafenib combined with ATG7 antagonistic therapy significantly inhibited the growth of melanoma." (PMID 32528867, 2020). "In particular, melanocyte-specific Atg7 or Atg5 ablation can prevent melanoma formation and drive melanocytic senescence in the same GEMM model, being the Atg7-related phenotype associated with increased oxidative stress and extended survival rate." (PMID 31998652, 2019). "Xie and colleagues have demonstrated that ablation of Atg7 in a BRAFV600E/PTENnull melanoma model decreased tumour growth, promoted senescence, and increased survival in comparison to mice that were wildptype for Atg7." (PMID 31416288, 2019). "In melanoma cells, miR-290-295 cluster suppressed autophagic cell death in response to glucose starvation through the down-regulation of ATG7 and ULK1." (PMID 26878873, 2016). "Correspondingly, ATG7 in a genetically induced melanoma mouse model was required for MTX-dependent growth inhibition that was reliant on functional CD4 and CD8 T cells." (PMID 27933272, 2016). "A number of BRAF fusions are, however, novel, including ATG7–BRAF in melanoma, as well as ZC3HAV1–BRAF and FAM114A2–BRAF in thyroid cancer." (PMID 25204415, 2014). "Knockdown of expression of the essential autophagy gene product ATG7 resulted in cell death, indicating that survival of melanoma cells is autophagy-dependent." (PMID 23383069, 2013). "Our results show that genetic inhibition of autophagy through knockdown of the additional essential autophagy components Atg7 and Atg5 impaired melanoma cell growth in multiple cell lines, demonstrating the reliance upon autophagy for survival." (PMID 23383069, 2013). "In a mouse model of melanoma, ATG7 gene deletion accelerated disease onset and reduced overall survival, indicating that autophagic defects caused by ATG7 deficiency may counteract oncogene-induced senescence and promote melanoma development." (PMID 40497999, 2025).
melanoma (continued). "Atg7 undergoes APA in both mouse and human cells, raising the possibility that ATG7 3′ UTR length could influence human melanoma growth just as it does mouse melanoma." (PMID 38302465, 2024). "No nonsense, frame-disrupting, or recurrent missense mutations were observed across this cohort, confirming that ATG7 is not a common mutational target in clinical melanoma." (PMID 38302465, 2024). "At apparent odds with these findings, work by Xie and colleagues showed that Atg7 ablation failed to promote, but rather impeded the development of melanoma driven by BRAFV600E and allelic Pten loss and extended mouse survival." (PMID 36670319, 2023). "In line with this notion, additional findings showed that hemizygous loss of ATG5 occurred during melanoma progression, and reduced expression of ATG5 and ATG7 was observed in both primary and metastatic melanoma tissues likely due to deficiency of nuclear respiratory factor (NRF1)." (PMID 36670319, 2023). "Interestingly, some autophagy markers (Beclin-1, Atg7) were also upregulated in MET-treated melanoma cells." (PMID 35216470, 2022). "Furthermore, we identified NRF1 as a new transcription factor involved in the regulation of ATG5 and ATG7, improving our current understanding of the regulation of autophagy during melanoma development and progression." (PMID 34458153, 2021). "Moreover, in BrafV600E-driven and Pten heterozygous melanomas, Atg7 deletion dramatically suppressed tumor formation." (PMID 34298710, 2021). "Moreover, consistent with the reduced levels of ATG5 and ATG7, we found changes in the expression of autophagic activity markers, indicating reduced autophagy in melanomas as compared to benign nevi." (PMID 34458153, 2021). "Furthermore, the analysis of survival data of melanoma patients revealed an association between reduced ATG5 and ATG7 levels with an unfavourable clinical outcome." (PMID 34458153, 2021). "On the other hand, silencing of NRF1 could, in addition to the expression of ATG5 and ATG7, target several other genes, which could positively or negatively influence the migration potential of melanoma cells." (PMID 34458153, 2021). "Knockdown of Atg7 in melanoma cells impairs cell growth and induces cell death." (PMID 26134285, 2015). "To investigate the role of autophagy in melanoma cell growth and survival, we knocked down expression of the essential autophagy gene atg7 by infecting melanoma cell lines with two different shRNA-expressing lentiviruses directed against Atg7 or a luciferase control." (PMID 23383069, 2013). "Finally, to evaluate whether the AMBRA1 pro-autophagic function participates to the hyperactivation of FAK1, we silenced the key autophagy gene ATG7 (siATG7) in melanoma cells." (PMID 33953176, 2021). "On the contrary, others have demonstrated that loss of ATG7 in a BRAFV600E/PTENnull model of melanoma was associated with increased oxidative stress and senescence that prevented melanoma tumorigenesis, suggesting that inhibition of autophagy may also play a tumor-suppressing role." (PMID 32340261, 2020). "In addition, we depleted Atg7 in ovalbumin (OVA)-positive melanoma B16F10 cells." (PMID 32732922, 2020). "Indeed, existing reports of knockdown of the essential autophagy components Atg5 or Atg7 in the literature suggest that this approach results in increased cell death in different melanoma cell lines, although additional metabolic stressors may be required." (PMID 23383069, 2013). "Our results support the concept that reduced autophagic activity contributes to melanoma development and progression, and identifies NRF1 as a novel TF involved in the regulation of both ATG5 and ATG7 genes." (PMID 34458153, 2021). "We combined the LC3B data with an additional autophagic marker p62 and consistent with the expression of ATG5 and ATG7, we observed markedly lower LC3B and higher p62 levels in melanomas than in nevi, suggesting reduced autophagic activity in melanoma cells." (PMID 34458153, 2021).